LINC01360 (long independently transcribed non-coding RNA 1360)
Gene: Long non-coding RNA gene on chromosome 1 (73,305,609 to 73,355,255, forward strand). Ensembl gene ENSG00000233973.
Diseases named in the same sentence as LINC01360 in open-access papers:
LINC01360 is named in the same sentence as 4 diseases in open-access papers, as found by Europe PMC text mining. Sharing a sentence is not in itself a finding about the gene and the disease.
LINC01360 shares sentences with these, for which no sentence is quoted: autism spectrum disorder (1 paper); depression (1); migraine (1); schizophrenia (1).